FAS (Fas cell surface death receptor)
Diseases named in the same sentence as FAS in open-access papers (continued):
Sharing a sentence is not in itself a finding about the gene and the disease.
tumor (continued). "In addition, different γδ T cell subsets attach to tumor cells through the death receptors TNF-related apoptosis-inducing ligand receptor (TRAILR), CD95 (also known as FAS), and TRAIL and lyse cancer cells." (PMID 38077392, 2023). "However, MMR defects and other DDR defects induce the expression of FAS, FASL and TRAILR death receptors at the tumor cell surface." (PMID 37365643, 2023). "PDX-287R grafts treated with docetaxel also showed no change in tumor cell proportion and FAS expression at 1 week post-treatment, and a reduction in immune cell infiltration was observed." (PMID 37660083, 2023). "Moreover, MALAT1 upregulated the expression of CD36 and liposynthases (PPARγ, PGC1α, SREBP-1C, FAS, and ACC), enhancing unsaturated fatty acid synthesis and uptake, thereby promoting tumor cell progression." (PMID 37533434, 2023). "Previously, we revealed that FAS knockout in OSCC cells did not affect orthotopic tumor growth or cervical lymph node metastasis." (PMID 35249111, 2022). "FAS, BLC2L11, and PYCARD are responsible for the initiation of tumor cell apoptosis." (PMID 35408897, 2022). "A recent CRISPR screen identified an essential role for FAS-FASL in antigen-specific T cell killing, and tumor-cell eradication by tumor-specific CTLs and CAR-T cells was abrogated in FAS-deficient target cells despite the presence of activated and functional CTLs in vitro and in vivo." (PMID 35053524, 2022). "In addition, the FAS-FASL pathway is essential for the cytotoxicity of CTLs, including CAR-T cells, in the elimination of tumors in both tumor antigen-specific and antigen-independent manners." (PMID 35053524, 2022). "Finally, the FAS (CD95) and FASL axis is another mechanistic pathway by which CAR T-cells can mediate tumor cell killing." (PMID 34868059, 2021). "While the perforin and granzyme pathway requires target antigen expression on the cell surface of each tumor cell for its destruction, target antigen expression on each individual cell is not necessary for killing via the FAS-FASL pathway." (PMID 34771652, 2021). "As for T cell related cytotoxins, essential in tumor killing, stacked FPKM of 8 genes (PRF1, GZMM, GZMK, GZMH, GZMB, GZMA, FASLG, and FAS) demonstrated that these genes were more highly expressed 1.7-fold (P = 0.037) in IFNγ positive tumors compared to IFNγ negative tumors." (PMID 32265897, 2020). "The abnormal FAS/FAS ligand (FASL) pathway is not only related to tumorigenesis and development but also may be related to the sensitivity of tumor cells to some chemotherapy drugs." (PMID 33150184, 2020). "Noteworthy, many mechanistic studies that indicate a negative role of PTPN13 in FAS-induced apoptosis and suggest a pro-tumor function were performed in hematopoietic cancers." (PMID 33322542, 2020). "Indeed, Tao and colleagues showed that CD19+ IL10− B cells derived from tumor-draining lymph nodes (and in vitro activated) express FASL which triggers the apoptotic signal in 4T1 murine breast cancer cells expressing FAS." (PMID 31086070, 2019). "Moreover, FAS and CDKN1A were identified as the top downregulated genes in R1 cell-derived tumor xenograft versus parental cell-derived tumor xenograft." (PMID 31013771, 2019). "Although the tumor cells express high levels of FAS, the role of this signaling pathway in eliminating T-cells in the tumor microenvironment is not clear." (PMID 30518409, 2018). "Even more, triple negative tumors had more than twice as much FAS-positive tumor cells compared to ER-positive tumors." (PMID 28121628, 2017). "Of note, our in vivo results supported the inhibitory activity of 3-AWA on tumor growth and metastasis at as low as 5 mg/kg doses, illustrating moderately less expression of eIF4E/phospho-eIF4E, c-FLIP and elevated FAS expression, which were in accordance with our in vitro studies." (PMID 26728896, 2016). "The roles of FAS and FASL in tumor formation have been well studied." (PMID 26858129, 2016).
tumor (continued). "IL1RN inhibits PGE2, IL-6 production and MM cell growth, FTH1 is a favorable prognostic protein but is not really known to contribute to anti-tumor response and the death receptor FAS induces apoptosis in a large number of cell types." (PMID 26036313, 2015). "This may explain correlations between FAS and FASL and human carcinogenesis and/or aggressive tumor behavior." (PMID 24014103, 2013). "The RAC1, CDC42, FAS, and PDGFR signaling pathways all appear in the top 15 pathways with altered consistency (yet appear lower in our list according to activity) and have been shown to play a large role in GBM tumor formation." (PMID 21542931, 2011). "Tumour necrosis factor-related apoptosis-inducing ligand has been shown to exert enhanced apoptotic activity on tumour cells, while non-tumour cells have been reported to be resistant to TRAIL-induced death in many systems, whereas FASL kills only sensitive FAS-bearing cells by inducing apoptosis." (PMID 17551494, 2007). "Nevertheless, FAS expression pattern observed for both parental tumours was not altered in corresponding primary cultures, whereas only PAP60 downregulated FASR in mice xenografts." (PMID 17551494, 2007). "The FAS–FAS-L pathway maintains T-cell homeostasis by inducing apoptosis upon T-cell activation but also impacts lymphocyte differentiation, especially in the memory compartment, compared to naïve CD8+ T cells, which instead exhibit better intra-tumor persistence." (PMID 38891056, 2024). "Moreover, FAS-L expression by tumor endothelium hinders CD8+ T-cell infiltration and fosters FOXP3+ Treg predominance, while IFN-γ-driven FAS-L expression in MDSCs enhances their accumulation and induces apoptosis in FAS-expressing T cells." (PMID 38891056, 2024). "Through public data and experimental verification, we found that inhibiting the expression of EGR1 can regulate the invasion of tumour cells, and the decreased expression of EGR1 significantly upregulated the expression of E-cadherin and downregulated the targeted genes FAS and HSPG2." (PMID 37817210, 2023). "Expression of PD-L1 (the immune-checkpoint inhibit protein), CD47 (key molecule expressing ‘do not eat me signal’) and apoptotic protein FAS (also named TNFRSF6, Tumour Necrosis Factor Receptor Superfamily Member 6) are all crucial in participating the immune-escape mechanism of tumour cells." (PMID 35685372, 2022). "Interestingly, FAS do not enhance the anti-tumor effect of VC when there is concurrent exposure to PC3 and DU145 cells." (PMID 36139668, 2022). "It is reported that a low FASL/FAS ratio in tumors is a negative prognostic marker, and the administration of tumor-targeted antibodies fused to FASL could be a future therapeutic alternative in such patients." (PMID 35682983, 2022). "This phenomenon results in the selection of a subpopulation of tumor cells that are FAS-negative." (PMID 32082995, 2020). "In summary, depending on the tumor type, PTPN13 may regulate resistance to anti-cancer therapies through its anti-apoptotic role via the FAS pathway, or through regulation of secondary EGFR pathways (ephrinB1/ErbB and SRC/PKD1/AKT), or through an indirect action on microtubules mediated by ephrinB1." (PMID 33322542, 2020).
tumor (continued). "This may suggest that the aberration of FAS in tumours may be yielding the immune-evasion mechanism and that FASLG expression on tumour cells results in the inactivation of killer T cells and hence becoming resistant to FAS–FASLG mediated apoptosis." (PMID 32606315, 2020). "Unlike hematopoietic cancers where PTPN13 negative transcriptional regulation has an anti-tumor effect by sensitizing cells to FAS-induced apoptosis, PTPN13 negative transcriptional regulation in solid cancers has a pro-tumor effect through activation of proliferation pathways." (PMID 33322542, 2020). "The migrated effector T cells to GvHD target organs and/or tumor sites exert their cytotoxic functions through direct cell contact-mediated or cell contact-independent cytokine-mediated cytotoxic pathways, including FAS ligand (CD95L)/FAS and perforin/granzyme pathways." (PMID 32560120, 2020). "Therefore, alteration of the FAS and FASL expressions may decrease the apoptotic ability of cells, and many tumor cells may evade or suppress the immune system." (PMID 26858129, 2016). "Expression of FAS, DR3 and DR6 and DR downstream pro-apoptotic proteins including cleavaged caspase-3, -8 and -9 was concomitantly increased, but the NF-κB activity and expression of pI03BAB and nucleus p50 and p65 were inhibited in tumor tissues by treatment with BV." (PMID 25730901, 2015). "Therefore FAS/FASL system could be activated and FASL produced in the tumor microenvironment by pro-inflammatory and resident stromal cells could participate to the XPO-1 mediated cell death." (PMID 26620414, 2015). "Because increasing FAS expression and the FAS-mediated apoptosis pathway have been shown to increase the efficacy of CTL elimination of target tumor cells, we therefore aimed at testing the hypothesis that restoring FAS expression is sufficient to suppress metastatic colon-tumor growth." (PMID 35053524, 2022). "This evidence reveals that the status of FAS and PVR genes may represent a novel biomarker predicting the outcome of NB patients, thus suggesting that their restoration could improve disease status through an immunomodulatory action that could involve NK-cell-mediated innate anti-tumor functions." (PMID 34503178, 2021). "The decreased expression of FAS may keep the transformed cells from elimination by antitumor immune response, called immune escape while the increased expression of FASL may increase the ability of tumor cells to kill FAS-sensitive lymphocytes, called immune counterattack." (PMID 24587306, 2014). "We observed significantly increased gene scores for FAS, FASLG and TNFSF10 in C11_CD8 compared with the nondysfunctional/effector tumor-infiltrating CD8+ T cells and earlier dysfunction fates." (PMID 35668194, 2022). "We observed that 4/7 FAS genes, GPAT4, CHP1, PCGF1, and GPI, show significant, negative hazard ratios (HR), consistent with a tumor suppressor signature, and that no other gene from our set shows a negative HR." (PMID 34764293, 2021). "FAS also binds to FASL to activate the non-inherent apoptotic pathway, and tumor cells release transforming growth factor (TGF)-β and interleukin (IL)-10 to counterattack immune cells." (PMID 31737562, 2019). "The death of tumor cells mediated by FAS represents a mechanism independent of the T-cell receptors (TCR), so that if TCR affinity is low FAS has a potent cytotoxic role." (PMID 24672524, 2014). "In addition, these cytokines induce the expression of death molecules such as FAS and TRAL-R2 in tumor and non-transformed cells." (PMID 41102150, 2025). "However, neutralization of FASL failed to decrease tumor cell death, indicating that tumor-cell-produced FASL plays no significant role in tumor-cell FAS-mediated apoptosis, and the auto-oligomerization and auto-apoptosis are not caused by tumor-cell-produced FASL." (PMID 35053524, 2022).
cancer (379 papers, 1997 to 2025). A tumor composed of atypical neoplastic, often pleomorphic cells that invade other tissues. "Mutations, such as KRAS G12D, can also reduce FAS production, enabling cancer cells to evade immune surveillance and increase survival." (PMID 41188939, 2025). "Given the important role of the Fas receptor in various aspects of oncogenesis, variations in the FAS gene have been shown to influence the risk and prognosis of many cancers." (PMID 39416461, 2024). "While FAS is expressed in Tregs from healthy individuals and cancer patients, elevated FAS-L is seen only in Tregs from cancer patients, linked to poor CD8+ T-cell infiltration and FOXP3+ Treg predominance." (PMID 38891056, 2024). "For instance, FADD, FASLG, RIPK1, RIPK3, and TNF were more prone to copy number gain than loss in pan-cancer, but FAS and TLR3 displayed the reverse tendency." (PMID 37351504, 2023). "Although numerous studies have investigated the association of FAS polymorphisms with different types of cancer, limited data are available on their possible involvement in susceptibility risk and IM treatment response in CML patients." (PMID 33639675, 2021). "Although lymphoma has been reported as the most common type of malignancy seen in these patients, additional types of cancers in this population suggest a broader cancer predisposition as previously observed with somatic FAS mutations." (PMID 34484227, 2021). "Even though few studies have shown the association of FAS/FASL polymorphisms with susceptibility risk of various cancers, till date there is only one report on its association with CML susceptibility risk worldwide." (PMID 33639675, 2021). "Cancer-associated pathways such as integrin signaling pathway, inflammation mediated by chemokine and cytokine signaling pathway, Wnt signaling pathway and FAS signaling pathway appeared to be altered in both MM BMIF as well as serum." (PMID 33585190, 2020). "Many cancer cell lines develop resistance to FAS-induced apoptosis by acquiring mutations in the FAS gene or by regulating FAS availability at the cell surface." (PMID 33322542, 2020). "These proteins map to a number of ‘cancer-associated’ pathways such as the FAS signaling pathway, TGF-beta signaling pathway, angiogenesis and VEGF signaling pathways." (PMID 28086232, 2017). "The G to A substitution at rs2234767 in the silencer region of the FAS gene is reported to be associated with cancer risk, so that the AA genotype increases the risk of cancer, while the G-allele is a protective factor." (PMID 27009330, 2016). "DR4 and FAS mutations resulting loss or reduction of apoptotic function have been described in different human cancers." (PMID 24587306, 2014). "Higher levels of FAS expression were significantly associated with depth of carcinoma invasion (P=0.0423) and lymphatic invasion (P=0.0023)." (PMID 24527066, 2014). "Studies with larger samples to study gene-environment interactions are warranted to understand the role of FAS gene polymorphisms, especially -1377 G/A SNP, in cancer risk." (PMID 24014103, 2013). "To evaluate the genotype-genotype interaction, we analyzed the association between cancer risk and the combined genotypes of FAS-1377G/A and FASL-844T/C." (PMID 24014103, 2013). "Specifically, various single-nucleotide polymorphisms (SNPs) in apoptotic genes, such as FAS-1377 G/A SNP, have been associated with cancer risk." (PMID 24014103, 2013). "Many epidemiologic studies suggest associations between SNPs in FAS genes, mostly the FAS-1377 G/A SNP, and cancer risk." (PMID 24014103, 2013).
cancer (continued). "Individuals who carried both FAS-1377(GG+GA)/FASL-844(TT+TC) genotypes appeared to have lower risk of cancer than those who carried both FAS-1377 AA/FASL-844 CC genotypes." (PMID 24014103, 2013). "Down-regulation of FAS and cell death resistance is key to many cancers, but an association between FAS-1377 G/A SNP and cancer risk is uncertain." (PMID 24014103, 2013). "Individuals who carried both FAS-1377(GG+GA)/FASL-844(TT+TC) genotypes had a decreased cancer risk compared to those who carried both FAS-1377 AA/FASL-844 CC genotypes (OR = 0.47, 95% CI = 0.25-0.90, Pheterogeneity = 0.000, P = 0.023)." (PMID 24014103, 2013). "In summary, in the present meta-analysis, a significantly decreased association was found between FAS-1377 G/A SNP and cancer risk." (PMID 24014103, 2013). "Through a meta-analysis of these recent publications, we identified several novel data points, and to our knowledge, ours is the most comprehensive meta-analysis in the literature to study the association between the FAS-1377 G/A SNP and cancer risk." (PMID 24014103, 2013). "In the ethnicity subgroup analysis, we found that a significant association between the FAS-1377G allele and a decreased risk of cancer in Asians, suggesting genetic-based ethnic diversity." (PMID 24014103, 2013). "In the overall analysis, a decreased association was found between the FAS-1377G allele and cancer susceptibility in the three genetic models." (PMID 24014103, 2013). "Blocking EGFR signaling could increase susceptibility to FAS-mediated apoptosis, making it a promising therapeutic target in cancer." (PMID 41188939, 2025). "Furthermore, cancer cells infrequently express elevated levels of cFLIP or a mutant form of FAS/FAS-L, which can also cause resistance to FAS-mediated apoptosis." (PMID 39056676, 2024). "Loss of DR4 and FAS indicated death outcomes in cancer patients." (PMID 38791085, 2024). "FAS cell surface death receptor (FAS) positively regulates the extrinsic pathway of apoptosis and its overexpression may therefore reduce the survival of A549 cells; however, FAS overexpression has also been linked to cancer stem cell promotion." (PMID 38674080, 2024). "As PTPN13 induces resistance to FAS-mediated apoptosis, several studies evaluated whether resistance to cancer treatment is associated with PTPN13 expression." (PMID 37895093, 2023). "In a wider perspective, a relationship between cancer risk and FAS polymorphisms is controversial." (PMID 35059842, 2022). "A meta-analysis argues for a reduction of cancer risk in individuals bearing FAS-1377 G/A SNP." (PMID 35059842, 2022). "FAS belongs to the tumor necrosis factor receptor family and its mutations affect the death domain fostering anti-apoptotic properties leading to disrupted protein function and empowering cancer cells with survival advantages." (PMID 34494161, 2022). "Genetic variations such as SNPs in FAS may have a contributory sole in altering cancer susceptibility risk, including CML." (PMID 33639675, 2021). "As PTPN13 induces resistance to FAS-mediated apoptosis, several studies evaluated whether resistance to cancer treatment is associated with PTPN13 expression (see chapter 2.1)." (PMID 33322542, 2020). "These future studies could lead to a better and more comprehensive understanding of the association between the FAS-1377 G/A polymorphism and development of cancer risk." (PMID 24014103, 2013). "In addition, there are a large number of studies that had shown that up-regulation of FASL and/or down-regulation of FAS expression were observed in many human cancers and were associated with development of cancers, including NB." (PMID 23951214, 2013). "Alternative splicing of FAS is linked to apoptosis resistance in cancer." (PMID 23758675, 2013). "Possibly, individuals who carry the FAS-1377 A allele and smoke may have a higher risk of cancer, and this concept was supported by the data in our meta-analysis." (PMID 24014103, 2013).